RHOA (ras homolog family member A)
Diseases named in the same sentence as RHOA in open-access papers (continued):
Sharing a sentence is not in itself a finding about the gene and the disease.
Hypertension (continued). "On the other hand, the contribution of RhoA/Rho kinase signaling to the pathogenesis of human essential hypertension is less documented, although the enhanced involvement of Rho kinase in increased peripheral vascular resistance and cutaneous vasoconstriction was reported in hypertensive patients." (PMID 28197417, 2017). "And inhibition of RhoA/ROCK pathway with fasudil can reduce the high blood pressure and urine protein levels as well as the concentration of s-Flt in peripheral and umbilical blood in a dose-dependent manner, thus resulting in prevention of the development of PE." (PMID 29262624, 2017). "TCTP over-expression-induced RhoA activation indicates that silencing of cellular TCTP may offer therapeutic approaches for the regulation of hypertension by inhibiting RhoA/Rho kinase pathway and modulating vascular contractility." (PMID 24918292, 2014). "In this context, agents reducing the abnormally elevated intracellular TCTP in VSMCs and thereby down-regulate RhoA signaling might help in the therapy of systemic hypertension." (PMID 24918292, 2014). "Therefore up-regulation of RhoA/Rho kinase axis that induces the inhibition of MLCP appears to have a role in the regulation of vascular contractility in hypertension." (PMID 24918292, 2014). "Additionally, in experimental hypertension, direct RhoA/Rho-kinase inhibition also normalizes overexpression of genes that promote vascular remodeling." (PMID 22315665, 2012). "RhoA/Rho-kinase antagonists also have therapeutic potential in hypertension." (PMID 22444253, 2012). "However, overactivation of the PLK-1 → RhoA → actomyosin pathway may contribute to pathological vascular remodeling and hypertension by increasing vascular resistance and promoting excessive smooth muscle contraction." (PMID 41227386, 2025). "However, this is merely a hypothesis based on some indirect evidence, and whether the RhoA/ROCK signaling pathway is truly involved in BTKi-mediated hypertension remains to be confirmed by further studies in the future." (PMID 40453665, 2025). "Additionally, proteomics analysis of their aortic tissues revealed higher expression of RhoA, along with other proteins involved in the actin cytoskeleton organization, indicating that arterial stiffness, as well as hypertension, were dependent on a similar mechanism governing cellular stiffening." (PMID 36292250, 2022). "Moreover, in vitro experiments were not performed, and future studies applying ARHGEF11 gene knockout technology will provide a more detailed view of the molecular changes, combined with cellular level changes, in hypertension induced by activating the RhoA/ROCK signaling pathway." (PMID 35811723, 2022). "Therefore, we hypothesized that the RhoA/ROCK pathway may be involved in the occurrence of hypertension induced by TKIs and that ROCK pathway inhibitors may have a therapeutic effect on this hypertension." (PMID 35811723, 2022). "In this experiment, we further found that Y27632 inhibited ROCK and RhoA activity caused by activation of the RhoA/ROCK pathway induced by apatinib and HSD, which may be a potential therapeutic target for the treatment of hypertension caused by apatinib and HSD." (PMID 35811723, 2022). "Thus, loss of Cullin3 may result in disturbed RhoA stability, ROCK activity and elevated contraction and hypertension." (PMID 34136490, 2021). "Another important mechanism for hypertension is neutrophil infiltration into the systemic vasculature, which releases reactive oxygen species that might activate the RhoA/ROCK pathway, which in turn phosphorylates MYPT1 to enhance vascular reactivity in preeclamptic women." (PMID 34357074, 2021). "In addition, inhibition of RhoA/ROCK pathway with fasudil can reduce the high blood pressure and urine protein levels as well as the concentration of s-Flt in peripheral and umbilical blood in a dose-dependent manner, thus resulting in prevention of the development of PE." (PMID 29262624, 2017).
Hypertension (continued). "This review integrates recent mechanistic insights into RhoA/ROCK regulation of vascular function with clinical and translational perspectives on targeting this pathway in hypertension." (PMID 41301525, 2025). "This review synthesizes mechanistic and translational insights into RhoA/ROCK signaling in VSMCs and ECs, emphasizing its contribution to hypertension and cardiovascular disease, and evaluates current and emerging therapeutic strategies targeting this pathway." (PMID 41301525, 2025). "Aberrant RhoA/ROCK activation has been shown to increase vessel stiffening and clinical hypertension." (PMID 40777343, 2025). "Given its central role in modulating the RhoA/ROCK pathway, Pyk2 emerges as a novel therapeutic target for cardiovascular diseases characterized by hypercontractility, including hypertension." (PMID 40943595, 2025). "As such, RhoA/ROCK hyperactivity and increased substrate phosphorylation (e.g., MLC) have been identified as major contributors to vasoconstriction, clinical hypertension, and vascular aging." (PMID 40777343, 2025). "The RhoA/ROCK signaling axis plays a central role in VSMCs, calcium sensitization, arterial constriction and structural remodeling in hypertension." (PMID 41301525, 2025). "It has been shown that ceramides have the potential to activate Ras homolog family member A (RhoA)/Rho-kinase (ROCK) signaling, leading to vasoconstriction and hypertension in animal models similar to angiotensin II." (PMID 38137595, 2023). "Here, we discuss the mechanism of the contractile machinery in VSM, especially RhoA/Rho kinase and PKC/CPI-17 of Ca2+ sensitization pathway in hypertension." (PMID 34357074, 2021). "This is noteworthy as the RhoA/Rho kinase (ROCK) pathway plays a pivotal role in the development and maintenance of hypertension in animal models and in humans." (PMID 31936157, 2020). "It has been reported that the RhoA pathway plays an important role in Ang II-induced VSMC remodeling, stroke-prone spontaneously hypertension, cardiac remodeling, and vasoconstriction in rats, mice or beagles." (PMID 32751352, 2020). "RhoA/ROCK activation declined after six months of treatment with the AT1R blocker olmesartan, suggesting that the RhoA/ROCK pathway plays a major role in the development and maintenance of hypertension." (PMID 31936157, 2020). "Growing evidence indicates that RhoA and its main effector ROCK play a central role in a wide range of cardiovascular diseases such as congestive heart failure, atherosclerosis, and hypertension." (PMID 29467677, 2018). "Enhanced sympathetic nerve activity, which is characteristic for all three studied forms of experimental hypertension, is known to increase calcium entry through L-VDCC as well as calcium sensitization via RhoA/Rho kinase pathway." (PMID 28197417, 2017). "Along similar lines, evidence in aorta of mice indicated that the RhoA/ROCK pathway plays a fundamental role in PM2.5-mediated myocardial remodeling and hypertension." (PMID 28583124, 2017). "Fasudil, a RhoA/Rho kinase (ROCK) inhibitor, has been approved in Japan and China for treatment of cerebral vasospasm, stroke and hypertension." (PMID 27193833, 2016). "Taken together, TCTP seems to regulate RhoA/Rho kinase signaling pathways, implying that RhoA, pivotal player in the vasocontraction, is involved in the pathogenesis of TCTP-induced hypertension in TCTP-TG mice." (PMID 24918292, 2014). "Furthermore, Jak2‐mediated phosphorylation of ARHGEF1 at Tyr738 activates RhoA, increasing VSMC contractility and vascular resistance—a key mechanism in hypertension." (PMID 41020039, 2025). "Also, BTKis affect vascular development and tone regulation by activating the Notch and RhoA/ROCK pathways, leading to increased vasoconstriction and the advancement of hypertension." (PMID 40453665, 2025).
Hypertension (continued). "Clinical studies and drug interventions in animal models suggest inhibiting the RhoA/ROCK signaling pathway could mitigate vascular inflammation, prevent remodeling, and reduce high blood pressure." (PMID 40453665, 2025). "Moreover, several studies have confirmed that the RhoA/ROCK pathway plays a crucial role in the development of salt-sensitive hypertension and hypertension-induced cardiac hypertrophy." (PMID 39850566, 2024). "Of note, RhoBTB1 serves as a CRL3 substrate adaptor for the ubiquitination of PDE5, further suggesting that enhanced binding of variant CUL3 with substrate adaptors results in impaired substrate (i.e., RhoA and PDE5) ubiquitination and diminished vascular compliance in FHHt hypertension." (PMID 37845702, 2023). "Only 59 exhibited a significant RhoA-p115 complex GDP/GTP exchange inhibition potential (IC50 187 μM, 50.5% inhibition) in the Biacore assay, thus it could have a potential for treating high blood pressure." (PMID 37197584, 2023). "Consistently, dysregulation of RhoA/Rho kinase pathway has been reported in several hypertensive rat models, including SHRs, renal hypertensive rats, and deoxycorticosterone acetate (DOCA) salt-induced hypertensive rats." (PMID 36359240, 2022). "In conclusion, low-intensity ExT can reduce the blood pressure and improve cardiac architecture and functional damage through inhibiting RhoA/ROCK signaling pathway in SHR, which provides a new idea or target for the prevention and treatment of hypertension and hypertensive heart injury." (PMID 36284153, 2022). "RhoA and the Rho effector ROCK regulate vascular tone and hypertension." (PMID 34136490, 2021). "Our observation that RhoA kinase inhibition rapidly normalizes BP in the MLK3-KO mice demonstrates in vivo that disinhibition of RhoA is a major contributor to the hypertension in this model, and thus that MLK3 tonic inhibition of RhoA normally represses increases in BP." (PMID 34324442, 2021). "Thus, the activation of RhoA/ROCK is involved in the increment of Ca2+ sensitivity in VSMC and the vascular tone, which also affects the pathogenesis of hypertension and cardiovascular-renal disease." (PMID 33803946, 2021). "Thus, both RhoA and ROCK have been considered as therapeutic targets to prevent kidney damage and hypertension." (PMID 31500276, 2019). "Vascular actions of CUL3 may contribute to hypertension, because McCormick and colleagues proposed that CUL3 regulates vascular tone via RhoA/Rho kinase signaling." (PMID 28804198, 2017). "On the other hand, chronic studies do not support such an important role of RhoA/Rho kinase in the development of experimental hypertension, although this pathway seems to be critical for the severity of end-organ damage in hypertensive animals." (PMID 28197417, 2017). "RhoA could directly interact with ROCK and play important roles in many cardiovascular pathogenesis including arterial hypertension, atherosclerosis, heart attack, vascular remodeling, myocardial hypertrophy, and myocardial I/R injury." (PMID 26771557, 2016). "In addition, the involvement of the RhoA/ROCK pathway and actin cytoskeleton remodeling in hypertension/leptin-induced ROS formation and vascular hypertrophy were investigated in this study." (PMID 26557089, 2015). "Therefore, dysregulation of Ca2+ microdomains under oxidative stress may potentiate RhoA/ROCK activation, further contributing to vascular hypercontractility in hypertension." (PMID 41301525, 2025). "Furthermore, the RhoA/ROCK signaling pathway, which regulates smooth muscle contraction and cell migration, may also play a role in BTKi-induced hypertension." (PMID 40453665, 2025). "ET-1, as an upstream effector, increases the phosphorylation level of MLC through the RhoA/ROCK pathway, enhances vascular endothelial oxidative stress, increases peroxide production, reduces NO production through this pathway, and enhances vasoconstriction, leading to hypertension." (PMID 35811723, 2022).
Hypertension (continued). "Therefore, it is speculated that the RhoA/ROCK pathway is involved in the occurrence of hypertension induced by TKIs and that ROCK pathway inhibitors may have therapeutic effects on this hypertension." (PMID 35811723, 2022). "One of the limitations of this study might be that the AAA formation was induced by the pharmacological stimulation of AngII and BAPN in RhoA cKO mice, while human AAA is generally formed by the result of aging- and/or atherosclerosis-mediated hypertension and aortic wall vulnerability." (PMID 36207400, 2022). "It is generally accepted that Ca2+ sensitivity of myofilaments is under regulation by RhoA/Rho kinase-induced MLCP inhibition and that dysregulation of RhoA/Rho kinase signaling results in the hypercontractile properties of VSMC, thereby contributing to the pathogenesis of hypertension." (PMID 36359240, 2022). "Hence, Cullin3 limits RhoA-ROCK-mediated contraction and induces SMC relaxation, which may control vasodilation and protect against hypertension." (PMID 34136490, 2021). "In addition, two other pathways, the Notch and RhoA/ROCK signaling pathways, which regulate endothelial proliferation and vascular tone, have shown potential links to the BTK pathway and may contribute to the hypertension induced by BTKis." (PMID 40453665, 2025). "Although not all genetic variants in RhoA and ROCK1 genes were proved to be related to overall risk of PCa, we further conducted subgroup analysis stratified by age, smoke status, Pack-years of smoking, drink status, tea drinking, family history of cancer, hypertension and diabetes." (PMID 28184030, 2017). "In experimental hypertension, activation of ROCK signalling generates a negative feedback loop on the expression of vascular RhoA-GEFs, which influences ROCK-dependent contraction or remodelling in vessels under pathophysiological conditions, including hypertension." (PMID 29394331, 2018).
ovarian carcinoma (77 papers, 2010 to 2025). A malignant neoplasm originating from the surface ovarian epithelium. "Studies have shown that overexpression of the mechanosensitive encoding of actin cross‐linking/gelling protein TAGLN in ovarian cancer can mediate ovarian cancer stiffness regulation progression through RhoA/ROCK pathway." (PMID 39801760, 2025). "Our previous research found that RhoA is overexpressed in ovarian epithelial cancer, and its expression is positively associated with FIGO stage and differentiation." (PMID 33483472, 2021). "RhoA GTPase regulates several aspects of tumorigenesis and aberrant expression is associated with poor tumor differentiation and advanced stages of ovarian cancer." (PMID 32443784, 2020). "RhoA is a Rho GTPase able to regulate many aspects of cell invasion and its expression is associated with advanced stage of ovarian cancer." (PMID 32512900, 2020). "Within the lipid-rich ascites of ovarian cancer, PUFAs inhibit RhoA-GTPase activity, leading to the downregulation of nuclear YAP1, a critical transcription factor in the Hippo pathway, which dampens antitumor immune responses." (PMID 40330466, 2025). "One case study found that in the FIGO stages of ovarian cancer, the expression levels of RhoA mRNA were significantly higher in stage III-IV tumors than in stage I-II." (PMID 40655948, 2025). "Current researchers are still unable to explain why Rac and RhoA antagonize each other but simultaneously promote the occurrence and development of ovarian cancer." (PMID 40655948, 2025). "RhoA/ROCK pathway is implicated in various diseases, including ovarian cancer, chronic headache, traumatic brain injury, Parkinson’s disease, stroke and other neurological disorders." (PMID 40495884, 2025). "After leptin binds to OB-Rb on the surface of ovarian cancer cells, it can increase the expression of RhoA and activate the RhoA-ROCK pathway." (PMID 40655948, 2025). "SRPX also regulates the migration and invasion of ovarian cancer through the Ras homolog family member A signaling pathway." (PMID 39010084, 2024). "The NBDep method also identified 43 missense driver genes in ovarian cancer having a significant protein–protein network (p-value = 2.12e−06) where well-known genes such as RHOA, PIK3CA, and ATM are among these genes." (PMID 38195844, 2024). "Otherwise, KRAS, ERBB2, and RHOA are all in connection with ovarian cancer, but little is known about the mechanisms involved in other ovarian functional regulation of these genes, and there are also only a few exosomal miRNA-related pieces of research." (PMID 38037065, 2023). "A facilitatory role for RhoA in inducing a more aggressive phenotype has been observed also in other malignancies, such as for instance lung adenocarcinoma, ovarian carcinoma and lymphoma." (PMID 35604542, 2022). "FPR2 can stimulate epithelial ovarian cancer (EOC) to secrete Th2 cytokines through ras homolog family member A (RhoA), increase the polarization of M2 macrophages, and promote the invasion and metastasis of ovarian cancer cells." (PMID 36120322, 2022). "RAN promotes membrane targeting and stabilization of RhoA to enhance ovarian cancer cell growth and invasiveness." (PMID 35836227, 2022). "This shows that the regulation of activation/inactivation cycling of RhoA is also needed in ovarian cancer cells for effective cell migration, however, this regulation seems to be StarD13-independent." (PMID 34958986, 2022). "FPR2 stimulated M2 macrophage polarization and promoted invasion and metastasis of ovarian cancer cells through RhoA." (PMID 34930387, 2021). "This study demonstrates that arginase regulation of ovarian cancer cells motility and adhesion involves autophagy-mediated inhibition of RhoA." (PMID 33423701, 2021). "In conclusion, here we identify, for the first time, an autophagy-mediated inhibition of RhoA that plays an important role in regulating ovarian cancer cells motility and adhesion in response to arginine depletion." (PMID 33423701, 2021).